MDM2 (MDM2 proto-oncogene)
Diseases named in the same sentence as MDM2 in open-access papers (continued):
Sharing a sentence is not in itself a finding about the gene and the disease.
cervical carcinoma (continued). "Here we demonstrated that IU1, as a pharmacological deubiquitinating enzyme USP14 selective inhibitor, dramatically decreased MDM2 expression, accompanied by blocking G0/G1 to S phase transition, reducing cell growth and triggering cell apoptosis in cervical cancer cells." (PMID 33061808, 2020). "Comparison of the different histological types of cervical cancer may also be warranted for future studies to determine whether the frequency of PIK3CA mutation and MDM2 polymorphism differ based on the histological types of cervical cancer." (PMID 31350972, 2019). "Furthermore, MDM2 is critical to cervical cancer development and progression." (PMID 33061808, 2020). "There was a significant downregulation of BCL-2 (p < 0.01), MDM2 (p < 0.0001), and CDK2 (p < 0.01) expression levels in the L. cornuta-treated cervical cancer cells compared to the NC." (PMID 39005932, 2024). "LINC02962, also known as lnc-CCDST, was found to be significantly downregulated in cervical cancer tissues and bind to pre-carcinogenic DHX9 and E3 ubiquitin ligase MDM2, thereby affecting cervical cancer cell invasion and angiogenesis." (PMID 37928532, 2023). "In cervical cancer cells, the proto-oncogene DHX9 binds to the lncRNA lnc-CCDST and MDM2 to regulate cell invasion and angiogenesis." (PMID 35410446, 2022). "High-risk human papillomavirus (HPV) impairs the interaction between MDM2 and DHX9 and the degradation of DHX9 by inhibiting the expression of lnc-CCDST, thereby promoting the movement and angiogenesis of cervical cancer." (PMID 36338707, 2022).
cervical carcinoma (continued). "Thus, the present studies support the notion that USP14/MDM2-mediated activation of the UPS and autophagy contributes to the antitumor effects of IU1 in cervical cancer cells through MDM2 degradation." (PMID 33061808, 2020). "The expression of NEDDL4, RNF6, MDM2 and TRIM11 is abnormal in cervical cancer." (PMID 32655987, 2020). "Comparison between samples with high and low expression revealed that neither Mdm-2, nor p21 can be used as markers of early pathological response after RT in early stages of cervical carcinoma." (PMID 16685270, 2006). "The nature of the relationship between MDM2 SNP309 (rs2278744) and cervical cancer is not clear." (PMID 25075210, 2014).
retinoblastoma (46 papers, 1996 to 2025). A malignant tumor that originates in the nuclear layer of the retina. "From the table, it can be deduced that in rare cases, retinoblastoma can be caused by a mutation on chromosome 12 of gene MDM2." (PMID 38540335, 2024). "For instance, the GWAS studies on retinoblastoma show that it is caused by MDM2 and CDKN1A mutations in addition to RB1 mutation." (PMID 38540335, 2024). "Mouse double minute 2 homolog (MDM2) promotes cancer cell survival in retinoblastoma (RB), with the underlying mechanism remaining elusive." (PMID 36741966, 2023). "Plotting the expression of genes known to be associated with retinoblastoma development, such as MDM2, DEK, SYK and HELLS, confirmed their upregulation in RB1ko when compared to RB1wt and RB1het and in the tumor specimens." (PMID 35565295, 2022). "Besides, retinoblastoma has also been associated with MDM2, the first modifier gene so far identified in retinoblastoma." (PMID 35960463, 2022). "Indeed, a recent study showed an association of the MDM2 309 G/G SNP with incidence of familial retinoblastoma." (PMID 22916154, 2012). "Our 3D models closely resemble retinoblastoma tumor tissue and can serve as a platform to assess innovative drugs or implement the promising results on the use of MDM2 inhibitors for retinoblastoma treatment." (PMID 41282624, 2025). "This project aims to investigate the anticancer activity of the MDM2 inhibitor, nutlin-3a, in the treatment of retinoblastoma using both conventional 2D in vitro models and more-realistic 3D-bioprinted models." (PMID 41282624, 2025). "We report that MYC and MYCN show consistently different dependence on MDM2 in cancer cell lines, yet similar abilities to induce MDM2 expression and MDM2-dependent proliferation in the retinoblastoma cell of origin." (PMID 33425720, 2020). "The tumour arises in RB-depleted cone precursors, and the retinoblastoma proliferation depends on the cone precursors features such as high expression of oncoproteins like MDM2." (PMID 32502182, 2020). "MYCN is enriched in human retinoblastoma cells to promote tumor outgrowth, although how MDM2 regulates MYCN is unclear." (PMID 32824373, 2020).
retinoblastoma (continued). "Conversely, ectopic overexpression of MYC as well as MYCN induced high-level MDM2 expression and gave rise to rapidly proliferating and MDM2-dependent cone-precursor-derived masses in a cultured retinoblastoma genesis model." (PMID 33425720, 2020). "In retinoblastoma cells, MDM2 transcription is in part driven by RXRγ, a cell lineage transcription factor in the cone precursor cell of origin, yet the basis for further MDM2 upregulation in retinoblastoma tumors has not been established." (PMID 33425720, 2020). "MDM2 is intrinsically expressed at high levels in maturing human cone and retinoblastoma cells, which is regulated by cone transcription factor RXRγ." (PMID 32824373, 2020). "Here, we show that MYCN overexpression upregulates MDM2 in a fetal retina model that recapitulates features of human MYCN-amplified retinoblastoma." (PMID 33425720, 2020). "The expression of MDM2 was 10–100-fold higher in NB1691 than any of our retinoblastoma cell lines, orthotopic xenografts, primary tumor or human fetal retinae." (PMID 22916154, 2012). "Immunoblotting confirmed expression of full length MDM2 in NB1691 cells but there was very little MDM2 protein expressed in the retinoblastoma cell lines or xenografts except for the Y79 retinoblastoma cell line." (PMID 22916154, 2012). "Here, we genotyped MDM4 SNP7, MDM4 SNP34091, and MDM2 SNP 309 in 44 retinoblastoma tumors, their corresponding blood DNA, and 3 human orthotopic xenografts." (PMID 22916154, 2012). "Here we quantify the expression of MDM4 and MDM2 mRNA and protein in human fetal retinae, primary retinoblastomas, retinoblastoma cell lines and several independent orthotopic retinoblastoma xenografts." (PMID 22916154, 2012). "Notably, the ectopic expression of MYCN induces MDM2 expression, leading to enhanced proliferation of cone precursor-derived masses in a retinoblastoma genesis model under culture conditions." (PMID 39802403, 2025). "Similarly, retinoblastoma cell proliferation depends on RXRγ, TRβ2, MDM2, and MYCN, implying that intrinsic L/M-cone factors contribute to the oncogenic state." (PMID 40767624, 2025). "We also assessed whether ectopic MYC and MYCN induce MDM2 in a manner that is critical to the onset of tumorigenesis in an intact retina model of retinoblastoma initiation." (PMID 33425720, 2020). "MDM2 has been proposed as a genetic modifier in retinoblastoma." (PMID 32824373, 2020). "Our finding that MYCN promotes MDM2 expression in the retinoblastoma cell of origin and that MDM2 promotes MYCN expression in retinoblastoma cells suggests that MYCN and MDM2 comprise a positive feedback circuit that initiates at the onset of MYCN-driven retinoblastoma genesis." (PMID 33425720, 2020). "High levels of MDM2 in retinoblastoma cells suppress p14ARF-induced apoptosis." (PMID 32824373, 2020).
retinoblastoma (continued). "BEZ235 systemic toxicity could also potentially be minimized by delivering it as localized therapy directly to the eye, as has been demonstrated with other small molecule inhibitors such as Mdm2 or Syk of other signaling pathways activated in retinoblastoma." (PMID 28445155, 2017). "Therefore, it is difficult to infer that the retinoblastoma tumor arose from MDM2 expressing cone photoreceptors in the human retina or MDM2 expressing amacrine cells in the mouse retina." (PMID 22916154, 2012). "MDM2 was expressed at low levels in these 52 human retinoblastomas." (PMID 22916154, 2012). "For example, MDM2 expression may be important for the initiation of retinoblastoma but it may be subsequently downregulated with concomitant upregulation of MDM4." (PMID 22916154, 2012). "Finally, gene expression for both N-MYC (ninefold) and MDM2 (1.9 fold) were upregulated in retinoblastoma compared to normal retina." (PMID 20664703, 2010). "Importantly, the addition of Nutlin, an MDM4/MDM2 antagonist led to death of retinoblastoma cell lines and synergized with traditional chemotherapy in an orthotopic retinoblastoma mouse model." (PMID 18489754, 2008). "Furthermore, there is an extensive literature on blocking Mdm2 and its effects on retinoblastoma." (PMID 37606819, 2024). "The present study examined the expression levels of high-mobility group (HMG)A1, Ki-67, mouse double minute 2 homolog (MDM2), and retinoblastoma (RB)with respect to NFPA recurrence." (PMID 28255749, 2017). "Sporadic retinoblastoma has not been analyzed for MDM2 or MDM4 polymorphisms." (PMID 22916154, 2012). "In our previous study on the effects of CEP-1347 on retinoblastoma cells, we showed that the CEP-1347-mediated inhibition of MDM4 expression increased the expression of MDM2 in one cell line but decreased that of MDM2 in another." (PMID 37686602, 2023). "Of these, only the dual MDM2/MDM4 inhibitor, ALRN-6924 in combination with cytarabine is under investigation in retinoblastoma." (PMID 36338723, 2022).